LPA (lipoprotein(a))
Description:
Apo(a) is the main constituent of lipoprotein(a) (Lp(a)). It has serine proteinase activity and is able of autoproteolysis. Inhibits tissue-type plasminogen activator 1. Lp(a) may be a ligand for megalin/Gp 330.
Synonyms: Lp(a); AK38; APOA; LP
Tractability: Small molecule: a structure with a bound ligand is known; it belongs to a druggable protein family. Antibody: its Gene Ontology location is reachable by antibodies, with high confidence; UniProt predicts a signal peptide or a membrane-spanning region.
Safety:
Unwanted effects reported when the protein is acted on. In parentheses: how it was acted on, where the effect was seen, and who reports it.
Coronary Artery Disease (source: ClinPGx)
Gene: Protein-coding gene on chromosome 6 (160,531,482 to 160,664,275, reverse strand). Ensembl gene ENSG00000198670.
Pathways (Reactome):
Transport of small molecules: LDL remodeling
Gene Ontology:
Molecular function: apolipoprotein binding; fibronectin binding; protein binding; serine-type endopeptidase activity; endopeptidase inhibitor activity; heparin binding
Biological process: blood circulation; lipid metabolic process; proteolysis
Cellular component: plasma lipoprotein particle; extracellular region
Genetic constraint (gnomAD): Loss-of-function variants: 193 observed, 183.87 expected, observed/expected ratio (o/e) 1.05, 90% interval 0.93 to 1.18. The synonymous counts are far from expectation, so gnomAD's model fits this gene poorly and the ratio says little. Missense variants: 1,821 observed, 1,653.8 expected, observed/expected ratio (o/e) 1.1, 90% interval 1.06 to 1.14. Synonymous variants: 707 observed, 586.39 expected, observed/expected ratio (o/e) 1.21, 90% interval 1.13 to 1.28.
Homologues: Orthologues: chimpanzee LPA (65% identical), Drosophila melanogaster CG33458 (2% identical), Drosophila melanogaster CG33459 (1% identical), mouse Gm6619 (1% identical), rat Lpal2 (1% identical), mouse 5430401F13Rik (1% identical). Paralogues in human: PRSS56 (5% identical).
Diseases named in the same sentence as LPA in open-access papers:
LPA is named in the same sentence as 135 diseases in open-access papers, as found by Europe PMC text mining. Sharing a sentence is not in itself a finding about the gene and the disease. The quoted sentences say what the papers report.
atherosclerosis (110 papers, 2006 to 2026). A disease characterized by the build-up of fatty material and calcium deposition in the arterial wall resulting in partial or complete occlusion of the arterial lumen. "Lp(a) as a risk factor for atherosclerosis and related diseases have recently received much attention, and the levels of Lp(a) is mediated through expression of the LPA gene, which encodes apolipoprotein (a), the unique protein component of Lp(a)." (PMID 41543641, 2026). "The LPA gene polymorphisms have been associated with peripheral andcoronary atherosclerosis (Mehrabi etal., 2000), and recently, a large scale geneticmeta-analysis showed the association of the rs10455872-G allelewith AVC." (PMID 31188921, 2019). "The discovery of lipoprotein(a) [(Lp(a)], and the fact that elevated Lp(a) is an independent risk factor for atherosclerosis and CVD, directed the research to find drugs which might decrease its levels in serum and therefore could prevent cardiovascular events in patients with elevated Lp(a) levels." (PMID 35890138, 2022). "Therefore, above result suggests that LPA gene may be the potential mechanism leading to atherosclerosis and associated with an increased level of Lp(a)." (PMID 29457025, 2017). "An established and well-known gene that was reported to be an independent genetic risk marker for atherosclerosis and CVD is LPA that encodes apolipoprotein (a) and gives rise to Lipoprotein(a) particles." (PMID 38961082, 2024). "On the contrary, the causative role of triglyceride-rich lipoproteins and LPA (Lp(A) or Apolipoprotein(A)) in atherosclerosis was supported by substantial human genetic evidence." (PMID 37570643, 2023). "New association signals from cross-ancestry GWASs included, for example, variants at PROCR, GRK5 and F11 (thrombosis), LPA and ATP2B1 (lipid metabolism, hypertension and atherosclerosis), SWAP70 (membrane ruffling) and LAMC1 (cerebrovascular matrisome)." (PMID 36180795, 2022). "While the LPA gene is only found in a subset of primates and hedgehog, several animal models have provided insight into the mechanisms of how Lp(a) increases atherosclerosis." (PMID 31340607, 2019). "CELSR2, FN1, SPARCL1, APOE, LPA, APOA5, and TGFB1 exhibit causal associations with both atherosclerosis and four cardiovascular diseases, suggesting their potential as therapeutic targets for atherosclerosis." (PMID 40649979, 2025). "Five of them (ANGPTL4, APOB, BRAP, LPA, and ZPR1), were associated with increased levels of arteriosclerosis/atherosclerosis and risk of CVD, whereas four (DUSP13, FN1, IL6R, and MMP12) were associated with reduced levels of arteriosclerosis/atherosclerosis and risk of CVD." (PMID 42133815, 2026). "The three most promising proteins (CELSR2, FN1, and SPARCL1) were identified as potential therapeutic targets for atherosclerosis, while APOE, LPA, APOA5, TGFB1, and AGER also hold potential as drug targets for the disease." (PMID 40649979, 2025).
coronary artery disease (84 papers, 2004 to 2026). "Data from genome-wide association and PROCARDIS (Precocious Coronary Artery Disease) cohorts linked 2 LPA single nucleotide polymorphisms to increased Lp(a) levels and coronary artery disease risk." (PMID 38753254, 2024). "The LPA gene encodes lipoprotein (a), which is a well-known and independent risk factor for coronary artery disease." (PMID 37372439, 2023). "In a large genetic study of over 48,000 single-nucleotide polymorphisms (SNPs) from 2100 genes in over 3000 participants with coronary disease and over 3000 controls, the region of the LPA gene had the strongest association with coronary disease." (PMID 36294361, 2022). "The relation between variations in the LPA gene with increasing the risk of coronary heart disease is dependent on population differences, sex, and age." (PMID 35090557, 2022). "Some genetic epidemiologic studies, including genome-wide association studies, have revealed the locus in the LPA gene, and some have specifically identified the rs3798220 SNP as being associated with an increased risk of coronary artery disease." (PMID 36303606, 2022). "Allele rs55730499-T of the LPA gene is known to be associated with increased levels of lipoprotein (a), coronary artery disease, and a short life expectancy." (PMID 35203469, 2022). "In contrast to this, the distribution of the biomarker lipoprotein A, which is a strong risk factor for coronary heart disease, is mainly explained by variants in the LPA gene on chromosome 6." (PMID 36704342, 2022). "Genome-wide association studies (GWASs) have identified the LPA locus as strongly associated with risk of coronary disease." (PMID 33769464, 2022). "A Genome Wide Association Study (GWAS) studied by R. Clarke showed that LPA gene variants were strongly associated with both an increased plasma levels of Lp(a) and an increased risk of coronary disease." (PMID 29457025, 2017). "Evidence from multiple genome wide association and Mendelian randomization studies, suggested that LPA gene variants (encoding Lp(a) lipoprotein) were strongly associated with both an increased level of Lp(a) lipoprotein and an increased risk of coronary disease." (PMID 27184891, 2016). "Polymorphisms in the LPA gene were associated with coronary artery disease (CAD)." (PMID 24776095, 2014). "Similarly, for the splice site variant in the LPA gene (c.4974-2A>G), which is a protective variant against coronary heart disease (MAFFinns=0.03213; MAFBritons=0.003076; OR=0.84), 36 200 cases and 50 000 controls is required to achieve 80% power at genome-wide significance level in Finns." (PMID 28145424, 2017). "In this scenario, Lp(a) is determined by the genetics of the LPA gene, specifically in three chromosomal regions (6q26-27, 9p21, and 1p13) and in two SNPs (rs10455872 and rs3798220) that were strongly related to coronary artery disease." (PMID 41373581, 2025). "It is important to note that the interactions between F2 rs3136441, LPA rs55730499, STARD3 rs881844, SCARB1 rs838880, and COBLL1 rs12328675 showed a strong contribution to the risk of coronary artery disease." (PMID 35203469, 2022). "A study included a total of 63,746 coronary artery disease (CAD) cases and 130,681 controls, indicating that the most potent genetic association with CAD was the LPA locus, which was more potent than LDL-, PCSK9-, and 9p21-related variants." (PMID 33681307, 2021). "Several SNPS, such as rs11591147 in PCSK9, rs1260326 in GCKR, rs10455872 in LPA, rs964184 in ZPR1, rs58542926 in TM6SF2, and rs182611493 in MAU2 have been clinically associated with multiple metabolic disorders, including coronary heart disease, hyperlipidemia, non-alcoholic fatty liver disease." (PMID 41608459, 2026).
coronary artery disease (continued). "In particular, in recent years, two common splice site mutations (G4925A and G4733A with 22% and 38% carrier frequencies, respectively) in the LPA KIV-2 repeat region were shown to have a pronounced Lp(a) decreasing effect, with a concomitant lower risk of coronary artery disease in the carriers." (PMID 37762189, 2023). "Two variants (rs10455872 and rs3798220) are both highly associated with increased plasma Lp(a), reduced LPA copy number (i.e. reduced KIV2 repeats), and smaller Lp(a) lipoprotein size—associated with an odds ratio for coronary artery disease of 1.5 for one variant and 2.57 for two or more variants." (PMID 33769464, 2022). "Six LPA polymorphisms (rs10455872,rs7765803, rs6907156, rs1321195, rs12212807 and rs6919346) were genotyped byTaqMan assays in 1,265 individuals without premature coronary artery disease.The presence of AVC was determined by computed tomography." (PMID 31188921, 2019). "In doing so, we discovered that completely knocking out the TSFM gene might result in inviability or a very severe phenotype in humans and that knocking out the LPA gene might confer protection against coronary heart diseases, suggesting that LPA is likely to be a good potential therapeutic target." (PMID 25078778, 2014). "The present study is the first to show that lipid-associated GWAS loci such as rs4420638 of APOC1, rs3136441 of F2, rs55730499 of LPA and rs6065906 of PLTP are susceptibility markers for coronary artery disease regardless of sex, age, and body mass index." (PMID 35203469, 2022).
diabetes (39 papers, 2006 to 2026). "Finally, when looking at PAD, LPA rs3798220-C was identified with decreased risk, even after Lp(a) adjustment and in the final stepwise model which included older age, increased levels of Lp(a) and presence of type 2 diabetes mellitus (T2DM)." (PMID 40002555, 2025).
myocardial infarction (39 papers, 2004 to 2026). Gross necrosis of the myocardium, as a result of interruption of the blood supply to the area, as in coronary thrombosis. "Genotyping of LPA gene rs3798220 in a group of cases revealed that 30% were C-variant allele carriers, of which one subject is homozygous (CC)—a 32-year-old male who had a myocardial infarction and whose Lp(a) levels > 500 nmol/L." (PMID 40002555, 2025). "Lysophosphatidic acids almost completely blocked mitochondria-dependent apoptosis in mesenchymal stem cells after myocardial infarction via the regulation of the p38 pathway by LPA(1/3)/Gi/ERK1/2 pathway-mediated MKP-1 induction." (PMID 34485199, 2021).
Stroke (37 papers, 2013 to 2026). Sudden impairment of blood flow to a part of the brain due to occlusion or rupture of an artery to the brain. "We decided to assess the association of atherosclerotic carotid artery stenosis and atherogenic stroke/TIA with four polymorphic variants of the CDKN2B-AS1 and LPA genes." (PMID 31824394, 2019).
dyslipidemia (24 papers, 2005 to 2026). "Although several studies have investigated risk factors for dyslipidemia, such as diet, obesity, and lifestyle, few studies have extensively investigated the relationship between insomnia and abnormal apolipoprotein levels (including ApoA-1, ApoB and LPA)." (PMID 38087303, 2023).
type 2 diabetes (20 papers, 2012 to 2026). "The association of known LPA SNPs and ApoA isoforms with microvascular complications in type 2 diabetes has never been investigated." (PMID 32152647, 2020).
ischemic stroke (19 papers, 2020 to 2026). A stroke disorder caused by obstruction of blood flow to the brain, due to thrombotic (local blood clot formation) or embolic (due to a blood clot or other material traveling from another site) event. "Further study is required to understand the mechanism of LPA mutations in ischaemic stroke." (PMID 34006274, 2021). "Here, we report a middle-aged female who suffered ischaemic stroke with a novel compound heterozygous deletion covering the KIV2 CNV in the LPA gene from China." (PMID 34006274, 2021).
Hypercholesterolemia (17 papers, 2015 to 2026). An increased concentration of cholesterol in the blood. "We also conducted an additional gene co-localisation analysis, identifying four genes, namely CELSR2, PCSK9, LPA, and APOE, co-localised with hypercholesterolaemia and IHD." (PMID 38144368, 2023). "Our analysis identified four colocalized genes, CELSR2, PCSK9, LPA, and APOE, that are involved in lipid metabolism and may contribute to the development of both Pure hypercholesterolaemia and IHD." (PMID 38144368, 2023). "In addition, it is known that GALNT2, LPA, SCARB1, and APOC1 are genes responsible for a hereditary form of hypercholesterolemia." (PMID 35203469, 2022).
Hypertension (16 papers, 2016 to 2025). The presence of chronic increased pressure in the systemic arterial system. "Ageing, sex, diabetes mellitus, hypertension, smoking, drinking, TC, TG, LDL-C, HDL-C, Lp(a), mRNA expression level of LPA gene, and five SNPs were included in the multivariate logistic regression model." (PMID 29457025, 2017).
aortic stenosis (15 papers, 2017 to 2026). Aortic valve stenosis is a aortic valve disease caused by the incomplete opening of the aortic valve. "Recent drug discoveries, including the application of gene silencing technology to regulate Lp(a) expression via its LPA gene, have paved the way for promising clinical trials in aortic stenosis patients." (PMID 40076529, 2025).
Obesity (15 papers, 2021 to 2026). Accumulation of substantial excess body fat. "In the presented research, we determined for the first time an association between LPA gene polymorphism (rs10455872) and obesity risk according to the log-additive inheritance model, regardless of gender and age." (PMID 35207726, 2022). "Genetic polymorphisms of the LPA gene may play an important role in susceptibility to obesity." (PMID 40722558, 2025). "The distribution of LPA genotypes in the children with obesity and the healthy controls was not significantly different from that of the HWE (p = 1.00, p = 1.00, respectively)." (PMID 40722558, 2025).
aortic valve calcification (11 papers, 2015 to 2024). "In 2013, a genome-wide association study implicated an association of a genetic variant in the apo(a) gene (LPA) and increased Lp(a) with aortic valve calcification and calcific aortic valve stenosis (AVS)." (PMID 37176660, 2023). "Lp(a) received increased attention in this field in 2013, when Thanassoulis and colleagues reported that a genetic variant in the LPA locus encoding Lp(a) showed genome-wide significance for the presence of aortic valve calcification and stenosis across multiple racial and ethnic groups." (PMID 30533416, 2018).
thrombosis (10 papers, 2022 to 2025). "Fourth, due to the plasminogen-like structure of apolipoprotein(a), Lp(a) is suspected to interfere with fibrinolysis, although only extremely elevated Lp(a) levels seem to be potentially associated with venous thrombosis in large-scale observational and genetic studies." (PMID 36066785, 2022).
acute coronary syndrome (7 papers, 2018 to 2026). Signs and symptoms related to acute ischemia of the myocardium secondary to coronary artery disease. "Among the variants involved in lipid metabolism, we identified a significant association between acute coronary syndrome and the G allele of rs10455872 in the LPA gene (OR = 2.69; 95% CI: 1.61-4.49)." (PMID 40257950, 2025). "Two variants were associated with acute coronary syndrome, rs10455872 in the LPA gene (OR = 2.69; 95% CI: 1.61-4.49) and rs429358 in the APOE gene (OR = 1.93; 95% CI: 1.30-2.87)." (PMID 40257950, 2025). "We observed a robust association between the G allele of rs10455872 in the LPA gene and the increased risk of acute coronary syndrome." (PMID 40257950, 2025).
atrial fibrillation (7 papers, 2021 to 2025). A disorder characterized by an electrocardiographic finding of a supraventricular arrhythmia characterized by the replacement of consistent P waves by rapid oscillations or fibrillatory waves that vary in size, shape and timing and are accompanied by an irregular ventricular response. "The results are as follows: an increase in LPA protein expression is a risk factor for atrial fibrillation, LDL, and MI but offers protection against TGs." (PMID 38065874, 2023).
heart failure (6 papers, 2013 to 2024). Inability of the heart to pump blood at an adequate rate to meet tissue metabolic requirements. "Colocalization between GlycA and heart failure identified three genomic regions harboring the LPA, ABO, and ZNF259 genes with PP.H4 values of: 99.7, 72.2%, and 70.1%, respectively." (PMID 38892172, 2024).
hyperlipidemia (6 papers, 2017 to 2026). "Additionally, mutations of the LPA gene can be the cause of a polygenic form of hyperlipidemia." (PMID 31795497, 2019). "This is not entirely surprising given the CHD PRS includes SNPs in pathways relevant to hyperlipidemia, such as two influential SNPs (rs186696265 and rs10455872) residing near the LPA gene, which is known to increase levels of lipoprotein (a), a well-established atherogenic lipoprotein." (PMID 32000781, 2020).
venous thromboembolism (6 papers, 2016 to 2024). Occlusion of the lumen of a vein by a thrombus that has migrated from a distal site via the blood stream. "A further study including 4607 cases with venous thromboembolism investigated the two LPA variants rs10455872 and rs3798220 and did also not find an association." (PMID 26896185, 2016).
aortic valve disease (5 papers, 2020 to 2025). "Multiple genetic and epidemiological studies conducted since 2013 have shown that variations at the LPA gene locus, which determines Lp(a) levels genetically and is unaffected by aortic valve disease, significantly increase the risk of developing AVS." (PMID 39465476, 2024). "Patients with aortic valve disease were genotyped for PALMD rs6702619, LPA rs10455872, and IL6 rs1800795 polymorphisms and circulating levels of interleukin-6 (IL-6) were measured." (PMID 36337884, 2022).
Sepsis (5 papers, 2021 to 2024). Sepsis is defined as life-threatening organ dysfunction caused by a dysregulated host response to infection. "Moreover, the LPA gene features an IL6 response element, implicating it in systemic inflammatory responses, such as sepsis, which consequently elevates Lp(a) levels." (PMID 39263966, 2024).
breast carcinoma (4 papers, 2017 to 2020). "The remaining four CNVRs overlapped with genes ZFP14, JAK1, LPA, PDGFRA and were also associated with RFS in breast cancer." (PMID 29116104, 2017).